FLI1 (Fli-1 proto-oncogene, ETS transcription factor)
Diseases named in the same sentence as FLI1 in open-access papers (continued):
Sharing a sentence is not in itself a finding about the gene and the disease.
Ewing sarcoma (continued). "Transcriptional activation of pericentromeric heterochromatin driven by EWS::FLI1 in Ewing sarcoma and TMPRSS2 fusion proteins in prostate cancer yield pathogenic RNAs, which transmit genotoxic stress." (PMID 38530366, 2024). "Immunohistochemical detection of FLI-1 has been widely used to diagnose vascular tumors or, more evidently, Ewing’s sarcoma." (PMID 38280044, 2024). "Fli1 has been broadly studied in Ewing’s sarcoma, but its function in γ-radiation-induced injury has been barely investigated." (PMID 39451223, 2024). "Pharmacological inhibition of P300/CBP disrupts the EWS::FLI1 transcriptional complex in Ewing sarcoma, leading to senescence and vulnerability to senolytics, providing a promising therapeutic strategy for this challenging cancer." (PMID 39367409, 2024). "In contrast, FLI-1 expression has been well established in Ewing’s sarcoma and vascular tumors; therefore, it serves as a useful diagnostic marker for these tumor types." (PMID 38280044, 2024). "The histopathological evaluation and molecular testing confirmed diagnosis of a EWSR1::FLI1 fusion Ewing sarcoma and resulted in postoperative TNM classification of ypT2b, pN0 (0/4 LN), L0, V0, Pn0, R0." (PMID 39575427, 2024). "In contrast, Ewing sarcoma usually displays its genetic specificity through the rearrangement of the EWSR1 gene that results in fusion with FLI1 to form an oncogenic chimeric protein called EWS-FLI1." (PMID 39682287, 2024). "In this case NGS allowed the identification of the ESWR1::FLI1 gene fusion and thereby resulted in the diagnosis of a pulmonary Ewing sarcoma." (PMID 39575427, 2024). "EWSR1::FLI1 can exert both activating and repressing functions, and both of these functions are of importance in Ewing sarcoma." (PMID 38611033, 2024). "Deletion of LIN28B led to decreased EWSR1::FLI1 expression, which affects the self-renewal and tumorigenicity of Ewing sarcoma cells." (PMID 36672331, 2023). "In our study, in order to identify the isoforms preferentially upregulated upon EWSR1::FLI1 knockdown in Ewing sarcoma A673 cells (that is, in the EWSR1::FLI1low phenotype), we analyzed in detail our RNAseq dataset." (PMID 37511533, 2023). "Although clinical applications of the CRISPR-Cas9 strategy in targeting the EWSR1::FLI1 fusion in Ewing’s sarcoma remain to be seen, there has been recent development of small molecule inhibitors to target the genetic fusion proteins of EWSR1::FLI1." (PMID 36980578, 2023). "Lowering the expression of EWS/FLI1 leads to alterations in the cytoskeleton of Ewing sarcoma cells, resulting in a larger and more spindle-like morphology, coupled with changes in adhesive properties." (PMID 37894854, 2023). "Taken together, these data suggest that loss of hnRNPH1 partially phenocopies the effects of MS0621 on EWSR1::FLI1-dependent phenotypes in Ewing sarcoma." (PMID 36793594, 2023). "Studies have reported that high expression of FLI1 promotes the generation and progression of a variety of solid tumors, such as Ewing's sarcoma, breast cancer, melanoma, prostate cancer and glioma." (PMID 36814284, 2023). "The stability of EWSR1::FLI1 mRNA in approximately 10% of Ewing sarcomas is regulated by the carcinoembryonic RNA-binding protein LIN28B." (PMID 36672331, 2023). "It has been demonstrated that DAX1 (NR0B1), an orphan nuclear receptor, is induced by the EWS/FLI1 oncoprotein and is highly expressed in Ewing’s tumors, suggesting that DAX1 is a biologically relevant target of EWS/FLI1-mediated oncogenesis." (PMID 37298283, 2023). "Recently, it has been proposed that EWSR1::FLI1 levels can fluctuate in Ewing sarcoma cells, giving rise to two cell populations." (PMID 37511533, 2023).
Ewing sarcoma (continued). "We confirmed DNA-binding specificity of the purified protein by comparing its binding with oligonucleotides specific for PAX3::FOXO1 or EWS::FLI1 (a tumor-specific fusion oncoprotein found in Ewing sarcoma) using SPR." (PMID 37732905, 2023). "However, dysregulated expression of Fli1 due to genetic mutations was recognized as one of the causative factors leading to malignant transformation of cells and the progression of multiple hematological and solid cancers, including Ewing’s sarcoma and prostate cancer." (PMID 36768203, 2023). "The Ewing sarcoma region 1 gene (EWSR1) was originally identified in the pediatric bone cancer, Ewing sarcoma, as a part of an aberrant fusion gene with FLI1." (PMID 36875767, 2023). "We had a similar experience when we discovered small-molecule inhibitors of EWS::FLI1 protein in Ewing sarcoma." (PMID 37732905, 2023). "These investigations have demonstrated that a considerable portion of the genes controlled by EWS/FLI1 in Ewing sarcoma cells also fall under the influence of DAX-1." (PMID 37894854, 2023). "Since DAX1 expression is positively regulated by EWS‐FLI1 in Ewing's sarcoma, we decided to knock down FLI1 instead of DAX1 to assess the gene signature profiles clearly." (PMID 36825574, 2023). "The EWS/FLI1 fusion protein functions as an abnormal transcription factor crucial for the development of Ewing tumors." (PMID 37894854, 2023). "O-GlcNAcylation of EWSR1::FLI1 was also reported to positively regulate oncogenic function in Ewing sarcoma." (PMID 36672331, 2023). "ChIP-sequencing of V5-EWSR1::ATF1 identified previously unreported motifs including the AP1 motif and motif comprised of TGA repeats that resemble GGAA-repeating microsatellites bound by EWSR1::FLI1 in Ewing sarcoma." (PMID 38136296, 2023). "These discoveries highlight that EWS/FLI1 inhibits FOXO1 activity through multiple mechanisms within Ewing sarcoma cells." (PMID 37894854, 2023). "EWSR1 (Ewing sarcoma breakpoint region 1) was originally identified as a part of an aberrant EWSR1/FLI1 fusion gene in Ewing sarcoma, the second most common pediatric bone cancer." (PMID 36875767, 2023). "Histone deacetylase inhibitors have also been shown to affect Ewing sarcoma cell proliferation possibly through EWSR1::FLI1-mediated transcription and chromatin regulation, although they have yet to demonstrate a clear signal in clinical testing." (PMID 36672331, 2023). "Cancers harboring transcription factor fusions such as EWS::FLI1 in Ewing sarcoma lack easily targetable pockets in their structure." (PMID 37509339, 2023). "depicts the IHC panel positivity in Ewing sarcoma, highlighting markers including CD(Cluster of Differentiation), FLI-1 (Friend Leukemia Integration 1), and P-63 (Tumor protein 63)." (PMID 37908610, 2023). "Investigations into how EWS/FLI1 boosts DAX-1 expression in Ewing sarcoma cells have unveiled an unexpected finding." (PMID 37894854, 2023). "Over the recent years, substantial endeavors have been dedicated to uncovering the functional significance of genes regulated by EWS/FLI1 in the context of Ewing sarcoma pathogenesis." (PMID 37894854, 2023). "Multiple E3 ubiquitin ligases have been observed to mediate EWSR1::FLI1 ubiquitination and degradation in Ewing sarcoma, including TRIM8 and SPOP." (PMID 36672331, 2023). "In 2006, NKX2-2 was identified as a gene regulated by EWS/FLI1 and was found to be crucial for the oncogenic transformation in Ewing sarcoma." (PMID 37894854, 2023). "EWSR1::FLI1 is necessary to maintain Ewing sarcoma proliferation and survival and exerts an ability to transform human primary mesenchymal stem cells." (PMID 36672331, 2023). "Recently, we identified 7Ai, a putative small-molecule OTUD7A inhibitor that suppresses EWSR1::FLI1 protein expression and subsequent Ewing sarcoma cell and tumor growth." (PMID 36672331, 2023).
Ewing sarcoma (continued). "Molecules were scored based on their ability to affect FAIRE signal at two FAIRE-enriched, EWSR1::FLI1-bound sites in Ewing sarcoma relative to regions of FAIRE signal shared by multiple cell types." (PMID 36793594, 2023). "CD44s, upregulated upon EWSR1::FLI1 knockdown, regulates cell migration and invasion in Ewing sarcoma cells." (PMID 37511533, 2023). "Ewing sarcoma is a cancer of children and young adults characterized by the critical translocation-associated fusion oncoprotein EWSR1::FLI1." (PMID 36793594, 2023). "Fli1 hyperexpression leads to malignant transformation of cells and progression of cancers such as Ewing’s sarcoma." (PMID 36768203, 2023). "EWSR1 is involved in many other translocations across sarcoma subtypes, including EWSR1::FLI1 in Ewing sarcoma." (PMID 38136296, 2023). "EWSR1 and EWSR1::FLI1 are known to cooperate to recruit the SWI/SNF complex to EWSR1::FLI1-bound loci, and SWI/SNF components have been implicated in Ewing sarcoma." (PMID 36793594, 2023). "Although the effect of the hnRNPH1 silencing seemed modest, EWSR1::FLI1 levels increased and Ewing sarcoma cell line proliferation was dramatically reduced." (PMID 36793594, 2023). "A classic example of transcription factor fusion is the EWSR1::FLI1 fusion, which is a common driver in Ewing sarcoma." (PMID 37509339, 2023). "Our research group has predominantly focused on looking up genes regulated positively or negatively by EWSR1::FLI1 in Ewing sarcoma cells (e.g., NR0B1/DAX1, CCK, LOX, SPRY1, DKK2, or FEZF1)." (PMID 37511533, 2023). "Reduction of EWS::FLI1 expression leads to changes in the Ewing sarcoma cell cytoskeleton that resulted in a larger and more spindle-like morphology that is associated with altered adhesive properties." (PMID 36505823, 2022). "Using these nanoparticles, EWS/FLI1 knockdown blocked in vitro and in vivo growth of Ewing sarcoma cells." (PMID 35220407, 2022). "Regulation of the level of EWS::FLI1 fusion protein in Ewing sarcoma cell begins with activation of the EWSR1 promoter, which serves as the promoter of the fusion gene." (PMID 36505823, 2022). "In Ewing sarcoma, disruption of AP1B1, a neighboring gene of EWSR1, has been shown to be caused by bridged chromoplectic rearrangements also fusing EWSR1 and FLI1." (PMID 36232302, 2022). "Knockdown of EWS::FLI1 expression in Ewing sarcoma cells induces transcriptomes that closely resemble MSCs." (PMID 36505823, 2022). "Although EWSR1-FLI1 gene fusion was traditionally considered pathognomonic for the diagnosis of Ewing sarcoma, it is well known that many partners other than FLI1 are identifiable." (PMID 36129618, 2022). "Fusions of EWSR1 exon 7 to either FLI1 exon 6 (EWSR1-FLI1 type 1) or exon 5 (EWSR1-FLI1 type 2), account for 60% and 25% of Ewing sarcoma-Friend leukemia integration (EWS-FLI) fusions, respectively." (PMID 36714878, 2022). "This has led to the premise that Ewing sarcomas are subject to the “Goldilocks” principle in which EWS::FLI1 must be maintained at just-right levels: too much fusion protein is toxic, while too little fails to maintain malignant properties." (PMID 36505823, 2022). "The efficacy of the treatment with YK-4-279 in inducing apoptosis and reducing tumor growth in Ewing’s sarcoma xenograft models and the high homology between FLI1 and other ETS members, in particular ERG, fostered the testing of YK-4-279 in PCa cells." (PMID 35267426, 2022). "In case #2 with relapsed EWSR1:FLI1-positive Ewing sarcoma, serial viable tissue sampling with DSP before and after therapy allowed us to monitor the evolution of drug resistance under multiagent chemo- and targeted therapy." (PMID 36575299, 2022). "Overall, investigation of epigenetic drugs for Ewing sarcoma treatment is still in its infancy but there is clear evidence that these agents can disrupt EWS::FLI1 transcriptional activity and inhibit fusion-driven gene signatures." (PMID 36505823, 2022).
Ewing sarcoma (continued). "We denoted the copy numbers of EWS/FLI‐1 mRNA in the original 10 μL aliquoted A673 Ewing sarcoma EVs and Click Bead‐captured A673 EVs as EWS/FLI‐1 mRNA spiked‐EVs and EWS/FLI‐1 mRNA captured‐EVs, respectively." (PMID 35486030, 2022). "The EWSR1/FLI1 fusion protein, which is identified in 85–90% of Ewing sarcoma tumors, and its direct targets are given special focus in this study." (PMID 35454895, 2022). "EWS::FLI1 “high” cells make up the bulk of Ewing sarcoma cells and are, in general, proliferative and relatively immotile." (PMID 36505823, 2022). "A minority of Ewing sarcomas express LIN28B which can directly bind EWS::FLI1 transcripts, promoting their stability." (PMID 36505823, 2022). "For instance, fusions involving EWSR1 and FLI1 drive Ewing sarcoma, which makes up 36.9% of bone cancers in AYAs compared to 12.3% in OAs." (PMID 36433963, 2022). "The alkylating agent trabectedin is a strong modulator of EWS::FLI1 activity and induces apoptosis in Ewing sarcoma cells." (PMID 36505823, 2022). "EWS::FLI1 expression plays an important role in regulating the sensitivity of Ewing sarcoma cells to these bone-derived signals." (PMID 36505823, 2022). "One study found that exposure of Ewing sarcoma cells to hypoxia resulted in upregulation of EWS::FLI1-repressed targets and downregulation of EWS::FLI1-activated targets." (PMID 36505823, 2022). "EWS::FLI1 is a master regulator of metabolic reprogramming in Ewing sarcoma cells and EWS::FLI1 knockdown increases glycolytic output." (PMID 36505823, 2022). "We found that gene editing at the exon 9 of FLI1 was able to block cell proliferation drastically and induce senescence massively in the well-studied Ewing sarcoma cell line A673." (PMID 34359682, 2021). "Investigation of the upstream regulatory mechanisms that control the phosphorylation of EWSR1/FLI1-Thr 79, thereby regulating its activity and promoting mitotic dysfunction, is essential for understanding the pathogenesis of Ewing sarcoma." (PMID 33293370, 2021). "We then used prostate cancer cells as a model to show androgen driven formation of a break in EWSR1 at the same breakpoint hotspot that creates the EWSR1/FLI1 oncogene in Ewing sarcoma." (PMID 34409300, 2021). "Although it is known that FLI1 cannot rescue the loss of EWS–FLI1 in Ewing sarcoma, we detected 3A mutation in both EWS–FLI1 and FLI1 alleles in A673 cells." (PMID 34060252, 2021). "One of the characteristics of Ewing’s sarcoma is the chromosome translocation that joins Ewing’s sarcoma breakpoint region 1 (EWS) to Friend leukemia virus integration 1 (FLI1)." (PMID 33435156, 2021). "The ntEWS PAS is in close genomic proximity to the sequence in EWSR1 that recurrently rearranges with FLI1 in Ewing sarcoma, the breakpoint hotspot." (PMID 34409300, 2021). "The FLI1 gene is an oncogene rearranged in 95% of Ewing sarcoma, a pediatric tumor of neuroectodermal origin." (PMID 34763718, 2021). "EWSR1 (Ewing sarcoma breakpoint region 1/EWS RNA binding protein 1) was initially identified as a translocation-generated fusion gene between EWSR1 and FLI1 in Ewing’s sarcoma and neuroectodermal tumors." (PMID 34612781, 2021). "7Ai treatment efficiently reduced EWS–FLI1 protein abundance in both Ewing sarcoma cells but had minimal effects on FLI1 proteins in HUVEC and FF cells." (PMID 34060252, 2021). "To answer this question, we turned to the well-characterized Ewing sarcoma A673 cell line with inducible EWS/Fli1 shRNA-mediated depletion." (PMID 33196691, 2020). "Here, we identify L1CAM as variably expressed in Ewing sarcoma, strongly induced upon EWS/Fli1 downregulation, and strongly associated in expression with adverse clinical outcome." (PMID 33196691, 2020).
Ewing sarcoma (continued). "Taken together, our studies uncover the existence of epigenetic mechanisms in Ewing sarcoma whose gene regulatory effects intersect those of EWS/Fli1 so as to promote disease properties in cells with high as well as low EWS/Fli1 expression." (PMID 33196691, 2020). "Ewing sarcoma is characterized by chromosome rearrangement which fuses the strong transactivation domain of EWS protein with the DNA binding domain of FLI1 protein." (PMID 32570740, 2020). "EWSR1 fuses with an E26 transformation specific (ETS) transcription factor, usually FLI1, to form the EWSR1-FLI1 oncogene that promotes Ewing’s sarcoma." (PMID 31494268, 2019). "Next, the Ewing sarcoma tumour is found to have EWSR1 (exon 10)-FLI1 (exon 8) translocation based on NGS." (PMID 30819134, 2019). "EWS/FLI1 knockdown by RNA interference has been shown to have tremendous effects on Ewing ́s sarcoma cell motility and adhesion." (PMID 31810195, 2019). "Ewing sarcomas are caused by a chromosomal translocation that fuses two transcription factors—EWSR1 and FLI1—together to generate the chimeric oncoprotein EWSR1-FLI1." (PMID 30939743, 2019). "A girl, born 2001, was diagnosed with primary disseminated EWS/FLI-1 positive Ewing sarcoma with a primary tumor in the mandible and skull metastases in December 2011." (PMID 31799177, 2019). "YK-4-279, a FLI1 inhibitor initially developed for Ewing’s sarcoma, was reported to shrink PCa tumors in ERG+ mouse xenograft models 111,112." (PMID 30135717, 2018). "Other proteomic studies have recently been carried out for soft tissue sarcomas with specific fusion genes such as EWS/FLI1 (for Ewing sarcomas) and PAX3/FOXO1 (for alveolar rhabdomyosarcoma)." (PMID 30680066, 2018). "Based on the pre-clinical data on EWS–Fli1 silencing, a phase I clinical trial has been designed for the treatment of Ewing sarcoma patients by a shRNA EWS/Fli1 type lipoplex (NCT02736565)." (PMID 29238848, 2018). "To further examine JIB-04 transcriptomic effects more specifically on the EWS/Fli1-driven gene expression program in Ewing Sarcoma, we performed gene set enrichment analysis (GSEA)." (PMID 30237855, 2018). "A number of different pharmacologic manipulations have been shown to alter EWS/Fli1 oncofusion levels in Ewing Sarcoma." (PMID 30237855, 2018). "Recent studies have shown that FLI1 is also aberrantly expressed in some solid tumors, including Ewing sarcoma, metastatic melanomas, nasopharyngeal carcinoma, and non-Ewing soft tissue tumors." (PMID 30537986, 2018). "In the present study, we sought to identify EWS/Fli1-repressed, growth suppressive, microRNAs potentially amenable to replacement in Ewing Sarcoma cells." (PMID 28542597, 2017). "In follow-up functional studies, we validated oncogenesis-modifying roles for several individual EWS/Fli1-regulated miRs or/and miR clusters in Ewing Sarcoma." (PMID 28542597, 2017). "It is well known that oncogenic activation of FLI1 leads to tumorigenesis, such as Ewing sarcoma and ovarian cancer." (PMID 28410216, 2017). "Their results showed that, in contrast to Ewing sarcoma, small cell osteosarcoma and mesenchymal chondrosarcoma lack FLI-1 immunoreactivity." (PMID 28439237, 2017). "Using global microRNA (miR) profiling, our laboratory previously identified miRs with altered expression as a function of EWS/Fli1 levels in Ewing Sarcoma, including miRs that were upregulated and others that were downregulated by the EWS/Fli1 oncoprotein." (PMID 28542597, 2017). "The markers of other sarcoma types, such as Ewing sarcoma marker, FLI‐1 38, chondrosarcoma or neurogenic sarcoma marker, S100 38, liposarcoma marker, PPARγ 39, and leiomyosarcoma marker h‐caldesmon 38, tested negative in tumors formed by SiRb‐OeMyc." (PMID 28191765, 2017). "To expand on our observation of miR-193b repression by EWS/Fli1, we compared miR-193b expression levels between Ewing Sarcoma cell lines and human mesenchymal stem cells (hMSC), a putative cell of Ewing Sarcoma origin." (PMID 28542597, 2017).